CD4 (CD4 molecule)
Diseases named in the same sentence as CD4 in open-access papers (continued):
Sharing a sentence is not in itself a finding about the gene and the disease.
tumor (continued). "Then RNA‐Seq data revealed that PAPPA2 mutation was significantly associated with higher activated CD4 memory T cells and lower Treg cells, suggesting an enhanced anti‐tumour immunity." (PMID 35811392, 2022). "In fact, a higher tumor infiltration degree by CD4+ T cells was associated with a favourable prognosis and a survival benefit in PCa patients." (PMID 36230505, 2022). "The infiltration of memory B cells, CD8+ T cells, CD4+ T cells, follicular helper T cells, DCs, NK cells, and M1 macrophages was associated with anti-tumor effects, whereas Tregs and M2 macrophages promote tumor growth." (PMID 35528236, 2022). "Combined with the bar diagram and the corresponding violin diagram, we found that most T cell types, including CD8+T cells and regulatory T cells, greatly the tumor tissues of patients in the high-risk group except for memory CD4+T cells in the resting state." (PMID 36591111, 2022). "The risk score had positive relations with most tumour-infiltrating immune cells, such as M2 macrophages and CD4+ T cells." (PMID 35692800, 2022). "When the disease progressed, the patient was retreated with mutation-reactive CD4 T cells and experienced tumour regression again." (PMID 35572552, 2022). "Flow cytometry analysis of the tumor at end-stage confirmed that DC vaccination caused tumor infiltration by both CD4+ and CD8+ T cells, which remained unchanged in combination with CM-272." (PMID 35634329, 2022). "Numerous peptides induce tumor-specific CD8+ CTLs and tumor-specific helper CD4+ T cells in association with class I and II major histocompatibility complex (MHC) molecules, respectively." (PMID 35660746, 2022). "Both systemic SHP2 inhibition and tumor cell–autonomous SHP2 depletion reduced tumor-infiltrated CD4+ T cells and M2-polarized tumor-associated macrophages." (PMID 36969745, 2022). "Tumor-infiltrating CD4+ T cells (C12_CD4) were associated with binding motif enrichment for cluster-specific TFs such as members of the POU domain family (POU2F1, POU2F2 and POU2F3), in addition to TF programs shared with dysfunctional CD8+ T cells." (PMID 35668194, 2022). "Adoptively transferred tumor antigen-specific CD4+ Th1 cells also accumulated in tumors and their presence increased the expression of M1-associated genes and proteins on tumor-associated macrophages in vivo." (PMID 36159781, 2022). "STMN1 was found to be linked with B cells, CD8+ T cells, CD4+ T cells, macrophages, neutrophils, and monocytes in tumor immune infiltration." (PMID 36127700, 2022). "Mechanistically, we find that FAK regulates interleukin-6, which can act in concert with interleukin-4 secreted by CD4 T-cells to drive elevated expression of PD-L2 on tumour-associated macrophages, dendritic cells and endothelial cells." (PMID 36138073, 2022). "Another personalized neoantigen long-peptide vaccine led to the expansion of neoepitope-specific CD8 and CD4 T lymphocytes in the primary tumor and metastases of an NSCLC patient with low tumor mutational burden (TMB)." (PMID 36654823, 2022). "In murine melanoma models, it was discovered that CD4+Foxp3+ T cells migrate to tumor areas through Nrp1 receptor signaling associated with VEGF ligands." (PMID 36203599, 2022). "In line with this notion, glucose deficiency can inhibit the anti-tumor effector functions of CD4+ T cells." (PMID 35812393, 2022). "Immune cell infiltration of the CD4+ subset in the tumor‐associated stroma was positively (strong) correlated to the infiltration of the CD8+ cell subset." (PMID 36177667, 2022). "The distribution pattern of CCR4 in tumor-associated CD4+CD25+CD127- Treg populations in healthy donor and tumor patients was determined using a comparative t-SNE method based on multi-color flow cytometry data." (PMID 35222362, 2022). "Specifically, CD4‐c02‐Itgb1 cells were linked to tumor‐enriched Tcm (CD4‐c05‐S1pr1) cells and Ifng+ Th1 (CD4‐c06‐Bhlhe40) cells based on STARTRAC‐tran indices." (PMID 36911291, 2022).
tumor (continued). "The higher the proportion of immune score in the tumor microenvironment, the better prognosis in most patients.In addition, tumor-infiltrating lymphocytes (TLSs), including CD4 and CD8 T cells, have been linked to increased survival rates." (PMID 35801082, 2022). "The high-risk group was negatively correlated with tumor-infiltrating immune cells such as hematopoietic stem cells and neutrophils and positively correlated with CD4 T cells and monocytes." (PMID 35249533, 2022). "CD4+ T-cell depletion also resulted in the downregulation of PD-L2 expression on tumour-associated macrophages, endothelial cells, and DCs." (PMID 36138073, 2022). "DP CD4+ Th TILs contain T cells that recognize tumor-associated antigens and tumor-specific neoantigens." (PMID 35439168, 2022). "More importantly, PD-1+ICOS+ CD4 Th cells were enriched in T cells recognizing tumor-associated antigens such as HPV but also tumor specific neoantigens." (PMID 35937775, 2022). "SA plays a clear role in both the recruitment of CD4+, CD3+ and F4/80 + immune cells and the differentiation of tumor associated macrophages (TAMs) into an M1 anti-tumor phenotype as well as promoting the pro-inflammatory actions of CD4+ T-cells." (PMID 36601581, 2022). "CIITA is a non-DNA-binding coactivator of major histocompatibility complex (MHC) class II molecules whose high expression is usually associated with enhanced involvement of CD4+ lymphocytes in tumor suppression and a better prognosis." (PMID 35425715, 2022). "CD8+ T cells revealed a stronger probability for tumor-associated exhaustion compared to the relatively exhaustion-resistant CD4+ population." (PMID 35177622, 2022). "In this study, we report that a high frequency of circulating CD4+FoxP3+ Tregs was associated with poorer disease-free survival (DFS), while their higher frequencies in tumor-infiltrating CD4+ Tregs was associated with better DFS." (PMID 35655158, 2022). "To this end, we obtained tumor microenvironment-associated cells derived from peripheral blood mononuclear cells (PBMCs), including CD4+ T cells, CD3+ T cells, CD8+ T cells, and DCs, as well as cancer-associated fibroblasts (CAFs)." (PMID 35982471, 2022). "In the tumor-draining lymph node of mice, Tmem176b deletion was associated with increased Caspase-1 activation in CD11b+ cDCs (cDC2) as well as with increased CD4+ RORγT+ cells versus WT animals." (PMID 36340035, 2022). "The idea that CD4+ Treg can be utilized to enhance anti-tumor immunity is paradigm shifting as Treg are associated with suppression of desired anti-tumor or anti-infectious responses." (PMID 35493508, 2022). "cDC2s induced CD4 T-cell proliferation in a tumor model, with antitumor activity produced by the loss of regulatory CD4 T cells." (PMID 36146572, 2022). "In line with this, the dependence on T cell immunity was evidenced by the loss of tumor controlling abilities when CD4 and CD8 T cells were depleted prior to administration of Salmonella + Alb-IL2." (PMID 35962391, 2022). "All three types of CD4+ T-cells and all dnT-cell types exhibited marked scores for ATLL signatures, but CD8+ T-cell types and NKT scored low, suggesting tumor malignancy of ATLL is more associated with CD4+ and dnT-cells than CD8+ and NKT cells." (PMID 35464471, 2022). "CD8+ T cells are vital effector cells in anti-tumor immunity, and the increased infiltration of CD4+ and CD8+ T cells in HNSCC tumor tissues is associated with favorable prognosis." (PMID 36531252, 2022). "There were more macrophages, macrophage-monocyte lineage cells, monocytes, neutrophils, and CD4+ Th1 cells infiltrated in tumor tissues of low-risk patients." (PMID 35382776, 2022). "In contrast, tumours responding to 5-FU (when administered as monotherapy or in combination) showed significant increases in tumour-associated NK+ cells and CD4+ TEM cells." (PMID 36289605, 2022).
tumor (continued). "The density of dysfunctional CD8 and the proximity of regulatory CD4 to tumor cells were independent risk factors for recurrence, and are positively correlated with the hypoxia response of CD8+ T cells and CAFs." (PMID 36685566, 2022). "We found that high levels of CD68 were associated with many immune cells in the tumor microenvironment, such as monocytes, abundant B cells, CD4+ and CD8+ T cells, dendritic cells, macrophages, and neutrophils." (PMID 35550532, 2022). "C12_CD4, which mainly comprised CD4+ T cells from tumors, was associated with high gene accessibility for markers of tumor-infiltrating regulatory T cells (Tregs), including TNFRSF18, ICOS and CTLA4." (PMID 35668194, 2022). "Higher infiltration by total CD3+CD8−(CD4+) T cells (including Tregs) within the PDAC tumor microenvironment was associated with longer overall patient survival (p = 0.001, Log rank Mantel–Cox test)." (PMID 36010856, 2022). "Eomes has also been implicated in programming other CD4 T cell subsets, such as Th9 cells, to become cytolytic and eliminate tumor cells." (PMID 36358898, 2022). "The HRisk group was associated with lower tumor purity, higher immune and stromal score, higher neutrophils, and lower activated memory CD4 + T cells." (PMID 35548187, 2022). "We found the activation of multiple biological pathways with the transition of tumor-associated macrophages and fibroblasts, and we identified the infiltration of CD4+CD25+ T regulatory cells in recurrent samples." (PMID 36553542, 2022). "CD4+ Th-CXCL13 recruits tumor-associated B cells and induces plasma cell differentiation and immunoglobulin production through interleukin-21 (IL-21) secretion and CD84 interactions in TLSs." (PMID 35663939, 2022). "The predominant tumor-infiltrating immune cells in the low-risk group were naïve B cells, monocytes, activated NK cells, plasma cells, CD4+ activated memory T cells, and CD8+ T cells." (PMID 35528236, 2022). "Visceral adipose tissue (VAT)-associated CD4+ Tregs are found in the omentum, producing high levels of IL-10 to constitute Treg subpopulation and then suppressing the anti-tumor immune system." (PMID 36503580, 2022). "The majority of transferred tumor-specific CD4+ T cells differentiated into Th1 cells and acquired cytolytic function, accompanied by a gradual loss of the expression of CD4." (PMID 35784297, 2022). "The lncRNA score was associated with tumor-infiltrating immune cell types, including activated B cells, activated CD4 T cells and monocytes." (PMID 35954243, 2022). "Tumor-associated macrophages switched from M2 to the tumor-killing M1 phenotype and promoted the recruitment of CD4+ and CD8+ T cells in the tumor microenvironment." (PMID 35935838, 2022). "The results indicated that pro-tumor immune cells of M2 macrophages and resting memory CD4 + T cells were found to be higher in the high-risk group." (PMID 35372408, 2022). "The immune-inflamed profile, characterized by CD8+ and CD4+ tumor-infiltrating lymphocytes (TILs), and PD-L1 expression on immune and tumor cells, is classically associated with better response to ICI." (PMID 35327458, 2022). "Cytotoxic T lymphocytes and tumor-associated macrophages prevail in the stroma while CD4+ T cells are predominantly found in the tumor epithelium." (PMID 36131941, 2022). "The levels of tumor-infiltrating immune cells (e.g., natural killer cells, DCs, macrophages, and CD4 + /CD8 + T cells) are associated with the immune response that is generated." (PMID 35155433, 2022). "DCs also reside in tumors, where they take up tumor-associated antigens (TAAs) and in turn migrate to tumor-draining lymph nodes in order to present these antigens to CD8+ or CD4+ T cells." (PMID 35454882, 2022). "Although both regorafenib and DC-101 (VEGFR2 receptor inhibitor) inhibit tumor angiogenesis, regorafenib induces tumor infiltration by CD4+ and IFN-γ+CD8+T cells, which is associated with better antitumor efficacy." (PMID 36119072, 2022).
tumor (continued). "Such LMP1 activated B cells have recently been shown to efficiently stimulate CD4+ T cells against tumor associated antigens (TAAs)." (PMID 35309359, 2022). "Of these immune cells, the M2 subtype of tumour-associated macrophages and CD4 Treg cells, as immunosuppressive cells, played a vital role in immune evasion and impacted ICB therapy." (PMID 35799269, 2022). "Two major subtypes of effector CD4+ T cells have the potential to cause damage to the tumor microenvironment, such as Th1 cells, which produce the pro-inflammatory cytokines IFN-γ and TNF-α, and Th2 cells, which produce IL-4 and IL-10." (PMID 35214685, 2022). "Studies have shown that increased levels of intratumoral CD4 T cells are associated with tumor progression and predict poorer patient survival in GC." (PMID 35237521, 2022). "In summary, our results provide new insights into the anti-tumor mechanisms of SGR, which plays an anti-tumor role by reversing the polarization of tumor-associated M1 to M2 macrophages and promoting the recruitment of CD4+ and CD8+ T cells in TAMs." (PMID 35935838, 2022). "This was rather unexpected since the majority of published studies link CD8+ T cells with effector tumor killing, while helper or regulatory functions are usually associated with CD4+ T cells." (PMID 35681695, 2022). "In KIRC, the infiltration of adaptive immune subpopulation, including activated CD8+ T cells, Tem/Tcm CD8+ cells, and Tem CD4+ cells, showed anti-tumor activity and associated with good prognosis." (PMID 35155261, 2022). "Most studies dedicated to achieving a better understanding of mechanisms underlying tumor progression and optimizing immunotherapeutic gains have focused on antagonizing Foxp3+CD4+ Tregs." (PMID 35703176, 2022). "Further research indicated that the severe thymic atrophy caused by VEGF-A infusion in a tumor-bearing mouse model was caused by a significant decrease in CD4+/CD8+ thymocytes." (PMID 36569915, 2022). "The failure of the adaptive antitumor immunity is also linked to the polarization of naive CD4+T cells in the tumor microenvironment." (PMID 35392957, 2022). "The increased content of self auto-induced factor 2, extracted from F.nucleatum in CRC patient feces, was associated with tumor immunity through tumor-associated macrophages and the CD4/CD8 ratio." (PMID 35749000, 2022). "Later studies further underlined the role of exhausted tumor-infiltrating tumor-Ag-specific CD4 T cells in the effector phase of the anti-tumor immune response." (PMID 35954341, 2022). "For example, the increased infiltration of CD8-positive lymphocytes into tumor tissues was reported to be associated with better clinical outcome of the patients, whereas that of CD4- and Foxp3-positive lymphocytes with their worse prognosis." (PMID 35565281, 2022). "Through the use of in vivo photoconversion, recent studies indicate that CD8+, CD4+, and gamma delta T cells access tumor-associated lymphatic vessels to egress from tumor microenvironments." (PMID 34651243, 2022). "The extent of intratumoral penetration of HCT-mono-mIL12 variants was strongly correlated with their tumor infiltration and intratumoral activation of CD4+ and CD8+ T cells to kill tumor cells." (PMID 36405748, 2022). "The presence of tsMHC-II is associated with increased CD4/CD8 tumour infiltrating lymphocytes, improved survival and responsiveness to ICIs." (PMID 35343573, 2022). "Compared to virus-specific Th1 cells, this tumor-specific CD4+ T cell state differentially expressed genes associated with Th2 cells, including Igfbp7, Ccl1, Ccr8, and Il13, and downregulated Th1-associated genes, including Ccl5 and Ly6c2." (PMID 35829695, 2022).
tumor (continued). "The tumor cell vaccine contains the whole tumor-associated antigens, including the epitopes of CD4+ helper T cells and CTLs." (PMID 35303904, 2022). "The number of tumor-infiltrating Tr1 cells (CD4+ FoxP3- IL-13- IL-10+) was associated with tumor-infiltrating pDCs, which enhanced Tr1-produced IL-10 via ICOS-L when exposed to tumor-derived factors." (PMID 35619702, 2022). "A higher level of CD4+ cells was associated with better outcomes of neoadjuvant therapy, and M2 macrophages in the tumour microenvironment have been reported to be associated with the occurrence of HPD43,44." (PMID 36104359, 2022). "In the breast tumor model, TGF-β is highly expressed on tumor-infiltrating B cells and associated with the conversion of resting CD4+ T cells to Treg cells." (PMID 36033455, 2022). "PD-L1+ monocytic tumor macrophages in the control group also showed a positive association between CD4+ and PD1+ CD4+ T cells which was ablated by SAR131675 treatment." (PMID 35681695, 2022). "In contrast to tumor-free mice, CD4+/CD8+ T cells in the pre-metastatic lung are deficient in the CD44−CD62L+ naïve T cell subset, indicating that they are activated." (PMID 35173168, 2022). "HNC Patients with higher 25(OH)D level also had higher levels of CD4+ T cell infiltration in the tumor and peritumor stroma and were associated with longer overall survival." (PMID 33732250, 2021). "This was associated with increased T-cell tumor infiltration and downregulation of CD4+ and FOXP3+ T-cells." (PMID 34439290, 2021). "In a tumor microenvironment, among other causes, exhaustion of CD4+ T-cell function is imposed by nutrient depletion, which is reversible in nutrient replete environments." (PMID 34548381, 2021). "Compared with the “Low-risk” group, the tumor and tumor thrombus tissue of patients in the “High-risk” group were featured with rich leukocyte infiltrates, such as CD4+ T cells, CD8+ T cells, as well as myeloid cells of macrophages and Neutrophils." (PMID 34993135, 2021). "We found risk score was significantly correlated with tumor-infiltrating immune cells including B cell naïve, B cell plasma, CD4+ T cells, Tregs, NK cells, macrophages." (PMID 34650975, 2021). "This exploratory analysis still provides suggestions of potential candidate genes as well as the signal pathways underlying tumor-infiltrating CD4+ T cells in TME and bestows a theranostic perspective to the current trend of research." (PMID 33301062, 2021). "It promotes recruitment of monocytes, MDSCs, CD4+ Th17 T cells, and NK cells, and is associated with tumor progression." (PMID 34359625, 2021). "We investigated the correlation between the risk score and the abundance of six tumor infiltrating immune cell subsets (i.e., B cells, CD4 T cells, CD8 T cells, macrophages, neutrophils, and dendritic cells)." (PMID 34143198, 2021). "The tumor microenvironment of these UBM-associated tumors was characterized by increased number of CD4+ T cells and NK cells, and fewer Tregs compared to control tumors." (PMID 34956223, 2021). "FOXP3 expression in cancer is usually associated with tumor-promoting CD4 T cells and the suppression of anti-tumor immune cells, such as effector CD8 T cells." (PMID 34638488, 2021). "These immune cells include tumor-associated macrophages, cytotoxic T cells, natural killer cells, B cells, CD4+CD25+FOXP3+ regulatory T cells, dendritic cells, and myeloid-derived suppressor cells." (PMID 33802331, 2021). "Since immune cell infiltration is very important in tumor progression, we next examined the relationship between the risk score and immune cells and found that it was related to B cells, CD4 T cells, and neutrophils." (PMID 33914773, 2021). "Since tumor-infiltrating lymphocytes (TILs: CD8+ cytotoxic T cells and helper CD4+ cells, regulatory T cells, B cells, NK cells), tumor-associated macrophages and myeloid-derived suppressor cells (MDSCs) are observed in some breast tumors." (PMID 33747948, 2021).